TIMP1 (TIMP metallopeptidase inhibitor 1)
Diseases named in the same sentence as TIMP1 in open-access papers (continued):
Sharing a sentence is not in itself a finding about the gene and the disease.
tumor (continued). "Similarly, the INHBA+ macrophage subset co-expressed pro-tumorigenic molecules such as IL6, TGFβ, TIMP1, CCL20, CXCL1, and IL10, highlighting the highly plastic and complex nature of tumor-infiltrating myeloid cells in vivo, consistent with recent similar studies in other solid tumors." (PMID 36439171, 2022). "Furthermore, um-PEA reduced tumor cell migration by reducing MMP2 and TIMP1 expression." (PMID 33923494, 2021). "Moreover, the serum TIMP-1 concentration was significantly elevated in patients with CRC in comparison to subjects with CA, and correlated with tumor stage, nodal involvement, the presence of distant metastases, patient survival, and tumor resectability." (PMID 34071492, 2021). "To further clarify whether inhibition of ITGB5 and activation of TIMP1 and TMEM176B affect tumor cell migration, we also used dCas9-KRAB-mediated CRISPRi technology to knock down ITGB5 expression, and used dCas9-VPR-mediated CRISPRa technology to induce TIMP1 and TMEM176B activation." (PMID 34109215, 2021). "In addition, the overexpression of TIMP-1 correlates with the elevated expression of MMP-9, and may stimulate tumor growth and malignant transformation as well as inhibit tumor cell apoptosis." (PMID 34071492, 2021). "To further clarify whether knockdown of ITGB5 and activation of TIMP1 and TMEM176B expression affect tumor cell invasion, we used dCas9-KRAB-mediated CRISPRi to knock down ITGB5 expression, and used dCas9-VPR-mediated CRISPRa to activate TIMP1 and TMEM176B expression." (PMID 34109215, 2021). "In order to further clarify whether ITGB5 is a proto-oncogene and whether TIMP1 and TMEM176B are tumor suppressor genes, we used dCas9-KRAB-mediated CRISPRi technology to knock down the expression of ITGB5, and used dCas9-VPR-mediated CRISPRa technology to activate TIMP1 and TMEM176B expression." (PMID 34109215, 2021). "In addition to being produced by the transformed or normal cells composing the tumor mass, MMP-9 is released in a TIMP-1-free form by neutrophils or macrophages which are recruited to the tumor site during the inflammatory response that accompanies cancer development or progression." (PMID 32630531, 2020). "In the present study, IL-6 was significantly shown to be modulated by TIMP-1 since genetically silencing TIMP-1 significantly decreased IL-6 mRNA and protein levels under normoxia, as well as hypoxia, the latter being a known critical player in tumor progression." (PMID 31443242, 2019). "Additionally, in statistical analyses, MMP-2 in tumor-stroma (T-S), MMP-9 (T-S), TIMP-1 (T-S), and TIMP-2 (T-S) variables were introduced in order to determine the differences in the expression of metalloproteinases and their inhibitors between the tumor and stroma." (PMID 31223594, 2019). "After eight treatments, TIMP1, MMP7, and TSP2 were significantly lower (P < 0.05) in the responding (gemcitabine + NAB‐P group) compared to the non‐responding tumors (gemcitabine group), thus suggesting they were potential markers for monitoring tumor response and treatment efficacy." (PMID 29941541, 2018). "Although FAS has been shown to be shed by MMP-7 in tumour cells, and addition of recombinant MMP-7 to hVSMCs did increase levels of sFAS (WRE unpublished data), we were unable to inhibit sFAS production with adenoviral overexpression of TIMP-1 or -2 which are potent inhibitors of MMP-7." (PMID 29617412, 2018). "However, based on the results obtained in the present study, the tumor TIMP-1 does not seem to reach the blood directly." (PMID 27619981, 2016).
tumor (continued). "Since TIMP-1 was discovered about two decades ago as a MMP inhibitor, it has been found to be expressed in various cell types such as fibroblasts, osteoblasts, epithelial and endothelial cells, smooth muscle cells, chondrocytes, mesenchymal stem cells, and many tumor cells." (PMID 27239203, 2016). "In the present study, the LX-2 human HSC line, induced by tumor-CM from human HCC cells, exhibited phenotypic characteristics, including increased cell proliferation, secretion of MMP-2 and gene expression levels of α-SMA, collagen I and TIMP-1, which are also induced by CD147." (PMID 25738354, 2015). "Furthermore, TIMP-1 analysis was performed on primary tumor tissue and not on corresponding metastases." (PMID 24884504, 2014). "Consequently, these findings are reflective of a more complex role for TIMP-1 in tumor metastasis rather than simply the regulation of MMP activity." (PMID 25036034, 2014). "In unadjusted analysis an estimated gain in median OS of nine months was seen in the doublet arm compared to the monotherapy arm for patients with a TIMP-1 negative tumor (GD, median OS: 19.9 months, 95% CI = 14.5-28.5; D, median OS: 10.6 months, 95% CI = 7.9-16.5, log rank p = 0.053)." (PMID 24884504, 2014). "Our data indicate that TIMP-1 in our model exhibits unequivocal effects, because it is tumor protective irrespective of whether host cells or tumor cells are targeted and irrespective of whether knockdown technology or over-expression technology is used." (PMID 22230683, 2012). "In addition, in residual tumour samples, the amount of MMP-9 mRNA seemed to be reduced at the end of RGZ treatment compared with that in the control group, whereas an opposite trend was observed for TIMP-1 expression." (PMID 20068562, 2010). "The immunoreactivity of VEGFA, bFGF, TGF-β, MCP-1, TSP-1, TIMP-1, TIMP-2, and endostatin was observed mainly in the tumor and non-tumor hepatic cells, showing a predominant cytoplasmic staining, with the positive liver cells distributed in both the tumor tissue and surrounding liver." (PMID 21152281, 2010). "Immunoreactivity to VEGF-A, bFGF, TGF-β, MCP-1, TSP-1, TIMP-1, TIMP-2, and endostatin was observed mainly in HCC cells and hepatocytes, showing a predominant cytoplasmic staining with positive liver cells distributed throughout the tumor tissue and the surrounding liver." (PMID 20716344, 2010). "In this study, practically none of the endothelial or tumor cells expressed TIMP-1 or TIMP-2." (PMID 18954439, 2008). "In addition, group 2 showed a significantly higher percentage of tumours positive for TIMP-1, MMP-9 and -11 in the tumour cells; as well as a significantly higher percentage of tumours positive for TIMP-2, TIMP-3, MMP-9, -11, -13 and -14, in fibroblastic cells." (PMID 17848954, 2007). "Although the antiproteolytic activity of TIMP-1 does not seem to be effective in tumor inhibition, we still wanted to address whether glycosylation macroheterogeneity affects this canonical function of TIMP-1 on selected classes of MMPs (collagenases, gelatinases, stromelysin, matrilysin)." (PMID 40345589, 2025). "Importantly, our study identified TIMP1, a key modeling gene, as being highly expressed in epithelial cells of LUAD patients, which might exacerbate the immunosuppressive phenotype of the tumor microenvironment by promoting the proliferation, differentiation, and infiltration of Treg cells." (PMID 41187171, 2025). "The balance between MMP-9 and TIMP-1 is thought to play a critical role in controlling extracellular-matrix turnover and the inhibition of tumor invasion and metastasis, therefore the decreased expression of TIMP-1 reported in our study may influence the tumor development and progression." (PMID 36518899, 2022). "In 5/19 (26 %) tumor samples, no specific TIMP-1 immunoreactivity could be detected." (PMID 36518899, 2022).
tumor (continued). "The novel role of TIMP-1 in promoting the infiltration/expansion of CAFs also suggests that TIMP-1 inhibitors developed in the future may have potentials to be used to block the CAF functions and therefore achieving their anti-cancer effects through attacking the tumor microenvironment." (PMID 24143225, 2013). "In CRC patients compared to participants without neoplasm, significant differences in blood levels of CRP, serum CD26 (sCD26), and tissue inhibitor of metalloproteinases 1 (TIMP-1) were observed." (PMID 39980561, 2025). "The transcriptomic analysis of the Groft scientific group showed a positive correlation between TIMP1 expression and a negative correlation of TIMP4 expression with tumor grade and malignant behavior, while the expression of TIMP3 and TIMP2 remained unchanged." (PMID 38474106, 2024). "Determining TIMP1 and TIMP2 mRNA levels confirmed that the correlation with tumor grade is negative." (PMID 38474106, 2024). "An interesting study was an analysis of TIMP1 expression carried out on available databases, i.e., UALCAN and Kaplan–Meier Plotter, which showed that tumor tissue fragments do not differ in expression from normal tissue." (PMID 37509417, 2023). "Identical results were obtained for tumor tissue patients with adjuvant chemotherapy (TIMP1 (p = 0.3108); MMP2 (p = 0.6402); MMP9 (p = 0.5738)) and without adjuvant chemotherapy (TIMP1 (p = 0.2654); MMP2 (p = 0.69); MMP9 (p = 0.5649))." (PMID 37509417, 2023). "Nevertheless, the effect of HIF‐1α on TIMP‐1 expression seems to be marginal in our case, as HIF‐1α silencing in 3D tumor spheroids did not alter TIMP‐1 at either the RNA or protein level." (PMID 35600659, 2022). "All neoplasms expressed MMP-2, MMP-9, MMP-14 and TIMP-1 independent of the infection state but displayed a variable distribution and intensity as demonstrated by immunohistochemistry." (PMID 33808256, 2021). "A pilot study demonstrated that TIMP-1 is a negative prognostic biomarker in clear cell RCC patients; conversely, EDA-A2 is known to act as tumor suppressor when it binds its receptor, XEDAR." (PMID 34440012, 2021). "The authors found that in the presence of CAF, there was an induction of a tumour invasive phenotype with increased expression of HGF and Tissue inhibitor of metalloproteinases 1 (TIMP-1) and disruption of the EC network, not observed with normal fibroblasts." (PMID 34572836, 2021). "In fact, this limitation is not restricted to TIMP-1 and CA19–9, the most established tumor marker for PDAC with a reported sensitivity of 79% and specificity of 82%, was shown to be influenced by jaundice." (PMID 29394913, 2018). "As TIMP-1 is secreted in the tumor microenvironment, we used a TIMP-1 neutralizing antibody to block TIMP-1 activity rather than use TIMP-1 knockdown cell lines." (PMID 27130446, 2016). "In the study from 2008, it was concluded that tissue-related TIMP-1 does not gain access to the blood stream proportionally with its level in the tumor and as such plasma TIMP-1 is not a surrogate marker for tissue TIMP-1." (PMID 24330623, 2013). "We then discerned that significant positive correlations between TIMP1 and CD8A were confined to instances where TIMP1 was expressed in the immune segment (highlighted in red), rather than with TIMP1 expression in the tumor segment (depicted in green) (lower correlation panels)." (PMID 38777826, 2024). "The involvement of the TNF-α and MMP-9/TIMP-1 complex in radiation-induced non-targeted effects led to the inhibition of tumor angiogenesis, highlighted by the 0.34-fold decrease in the MMP-9/TIMP-1 ratio in patients without AIT, which was only 0.8-fold in patients with coexisting AIT." (PMID 34298820, 2021). "The TIMP-1 high group included patients with higher TIMP-1 expression in HCC tissues, while the TIMP-1 low/non group included patients with lower or no TIMP-1 expression in tumor tissues." (PMID 25909286, 2015).
tumor (continued). "Separate analyzes of MMP1, MMP2, MMP3, MMP9, TIMP1, TIMP2, and MTC1 in plasma do not allow a prognostic prediction for tumour grading, staging, or metastasis, but certain combinations could be very helpful." (PMID 16901349, 2006). "Icam-1/CD54 and Timp1 levels, which showed difference in pancreas tissues from GEM mice, were either undetectable or comparable in CM from KPC sgSC and KPC sgUlk1 cells, suggesting that these factors probably originate from stromal fibroblasts rather than from tumor epithelial cells." (PMID 41408407, 2025). "The value of TIMP1, MMP7, and TSP2 as circulating biomarkers was corroborated in PDAC‐PDX‐bearing mice where the plasma levels of these molecules reflected the high levels found in the corresponding patient's plasma (data not shown) and correlated with tumor burden over time." (PMID 29941541, 2018). "Thus, increased TIMP-1 expression could be a progression marker in HCC development, indicating late tumor stages and dedifferentiation, rather than being a functional mediator of tumor initiation or promotion." (PMID 28386095, 2017). "Thus, despite tumour attenuation by inhibition of general MMP activity, TIMP-1 did not mimic this effect and, in fact, could promote tumour growth." (PMID 14612884, 2003). "The present study investigates the structure-function relationship of TIMP-1 for its interaction with CD63, which may eventually help design a novel approach for targeting TIMP-1’s pro-oncogenic activity without interfering its tumor suppressive MMP-inhibitory function." (PMID 32034211, 2020).
cancer (528 papers, 1992 to 2026). A tumor composed of atypical neoplastic, often pleomorphic cells that invade other tissues. "MMP-8 and the MMP-8/TIMP-1 ratio showed weaker associations with incident cancer and cancer mortality only in the 45-54-year age group." (PMID 42162053, 2026). "We investigated the associations of serum MMP-8, TIMP-1, and the MMP-8/TIMP-1 ratio with prevalent and incident cancer in 8448 individuals aged 25-74 years from the FINRISK97 cohort." (PMID 42162053, 2026). "The overexpression of TIMP1 or downregulation of TIMP3 is linked to cancer progression and poor prognosis in patients." (PMID 40244296, 2025). "The expression patterns of genes associated with high-risk signatures, namely MMP1, MMP12, and TIMP1, indicate their presence in a subset of macrophages, endothelial cells, and cancer-associated fibroblasts (CAFs)." (PMID 40362553, 2025). "This study establishes the impact of differential glycosylation on the disease (cancer)-associated multifunctionality of TIMP-1." (PMID 40345589, 2025). "To further investigate the immune associations of the three hub genes (PYGM, MAOB, TIMP1), we performed immune cell infiltration analyses across 33 TCGA cancer types using ssGSEA and CIBERSORT algorithms." (PMID 40873584, 2025). "TIMP1 is one of the main elements involved in maintaining tissue integrity but has recently emerged as a key actor implicated in various cancers." (PMID 40427104, 2025). "The enrichment of plasma-derived TIMP-1glyc1/1 in PC suggests a cancer-associated alteration in TIMP-1 glycosylation macroheterogeneity." (PMID 40345589, 2025). "It has been shown to play dual and contradictory roles in cancer progression, where elevated TIMP1 is consistently associated with poor prognosis in multiple cancer types." (PMID 41463352, 2025). "Here, these females show elevated levels of potassium and TIMP1, which in some studies have been associated with increased risk of cancer in humans." (PMID 41034487, 2025). "Yet, overexpression of TIMP1 by various cancer types has been associated with increased disease severity and pro-metastatic effects, partly mediated by TIMP1/CD63/ITGB1 activation of focal adhesion kinase (FAK) signaling." (PMID 40265926, 2025). "Aberrant expression of TIMP1 has been associated with the development and metastasis of certain cancers." (PMID 39518808, 2024). "TIMP1 is implicated in a variety of physiological and pathological processes, including tissue development, wound healing, inflammation, cancer, and cardiovascular diseases." (PMID 39518808, 2024). "High TIMP1 expression is strongly associated with a poor prognosis in almost all known cancer types, which corresponds with the observed increase in this marker at both the transcriptomic and proteomic levels, especially in the GBM group." (PMID 38474106, 2024). "It is known that in several human tumors, TIMP-1, once released from cancer or stromal cells, associates with CD63 at the cell surface, exerting its oncogenic role." (PMID 37443843, 2023). "Pan-cancer analysis revealed that Centromere Protein A (CENPA) and Metallopeptidase Inhibitor 1 (TIMP1) were highly expressed in most cancers and significantly associated with a poorer prognosis, also in ccRCC." (PMID 37213288, 2023). "Our innovative study deepens the understanding of the functional connections between TIMP1 and the mechanisms underlying cancer pathogenesis." (PMID 37842645, 2023). "The high expression of TIMP1 combined with the high proportion of Tregs, cancer-associated fibroblast, and MAST cell suggested a poor prognosis in GBM patients." (PMID 35685428, 2022). "As a specific hallmark of human cancer, TIMP‐1 plays multiple roles related to the TME and drug resistance." (PMID 35600659, 2022). "TIMP1 is associated with a poor clinical outcome for cancers and is suggested as a biomarker for cachexia." (PMID 36355178, 2022). "Elevated TIMP1 levels in bio-fluids (serum and plasma) are often associated with poor prognosis in various cancers." (PMID 35140332, 2022).